N4BP3 (NEDD4 binding protein 3)
Description:
Plays a positive role in the antiviral innate immune signaling pathway. Mechanistically, interacts with MAVS and functions as a positive regulator to promote 'Lys-63'-linked polyubiquitination of MAVS and thus strengthens the interaction between MAVS and TRAF2. Also plays a role in axon and dendrite arborization during cranial nerve development. May also be important for neural crest migration and early development of other anterior structures including eye, brain and cranial cartilage (By similarity).
Synonyms: LZTS4
Tractability: PROTAC: ubiquitination databases record sites on it.
Gene: Protein-coding gene on chromosome 5 (178,113,167 to 178,127,034, forward strand). Ensembl gene ENSG00000145911.
Subcellular location: Cytoplasmic vesicle; Cell projection, axon; Cell projection, dendrite
Subcellular location (Human Protein Atlas): Nucleoplasm; Centrosome
Gene Ontology:
Molecular function: protein binding
Cellular component: cytoplasmic vesicle; axon; dendrite
Genetic constraint (gnomAD): Loss-of-function variants: 33 observed, 41.59 expected, observed/expected ratio (o/e) 0.79, 90% interval 0.6 to 1.06. The upper end of that interval is the gene's LOEUF score, 1.06, which puts it in group 4 of 6, group 1 being the genes least tolerant of losing a copy. Missense variants: 756 observed, 752.13 expected, observed/expected ratio (o/e) 1.01, 90% interval 0.95 to 1.07. Synonymous variants: 326 observed, 324.38 expected, observed/expected ratio (o/e) 1, 90% interval 0.92 to 1.1.
Homologues: Orthologues: chimpanzee N4BP3 (99% identical), macaque N4BP3 (96% identical), pig N4BP3 (93% identical), rat N4bp3 (91% identical), mouse N4bp3 (91% identical), dog N4BP3 (90% identical), guinea pig N4BP3 (89% identical), tropical clawed frog n4bp3 (40% identical), zebrafish n4bp3 (32% identical), tropical clawed frog lzts1 (23% identical).
Diseases named in the same sentence as N4BP3 in open-access papers:
N4BP3 is named in the same sentence as 9 diseases in open-access papers, as found by Europe PMC text mining. Sharing a sentence is not in itself a finding about the gene and the disease. The quoted sentences say what the papers report.
asthma (1 paper, 2026). "Differentially methylated loci were near genes related to asthma (ITPR2, MAPK1), lung function (FKBP11), mitochondrial function (MRPL20, SPTBN1), inflammation (C3), and immune function (N4BP3, EIF5)." (PMID 41749276, 2026).
breast carcinoma (1 paper, 2025). "Another study reported that NEDD4-binding protein 3 (N4BP3) augments breast cancer metastasis through promoting EMT." (PMID 41385185, 2025).
colitis (1 paper, 2024). Inflammation of the colon. "The results indicate that N4BP3 knockdown in the colon tissue is able to reduce the degree of DSS-induced colitis in mice." (PMID 39420190, 2024).
hepatocellular carcinoma (1 paper, 2024). A malignant tumor that arises from hepatocytes. "In terms of tumors, N4BP3 is able to promote the expression of STAT2 by interacting with KAT3B, thereby promoting the angiogenesis in hepatocellular carcinoma, making N4BP3 a potential therapeutic target for hepatocellular carcinoma." (PMID 39420190, 2024).
N4BP3 also shares sentences with these, for which no sentence is quoted: colon cancer (1 paper); Crohn disease (1); inflammatory bowel disease (1); neurodevelopmental disorder (1); tumor (1).